FAXC (failed axon connections homolog, metaxin like GST domain containing)
Description:
May play a role in axonal development.
Synonyms: C6orf168; MGC2817; dJ273F20
Tractability: Antibody: UniProt predicts a signal peptide or a membrane-spanning region. PROTAC: its protein half-life has been measured.
Gene: Protein-coding gene on chromosome 6 (99,271,168 to 99,350,062, reverse strand). Ensembl gene ENSG00000146267.
Subcellular location: Membrane
Subcellular location (Human Protein Atlas): Nucleoplasm
Gene Ontology:
Cellular component: membrane
Genetic constraint (gnomAD): Loss-of-function variants: 7 observed, 39.96 expected, observed/expected ratio (o/e) 0.18, 90% interval 0.099 to 0.33. The upper end of that interval is the gene's LOEUF score, 0.33, which puts it in group 1 of 6, group 1 being the genes least tolerant of losing a copy. Missense variants: 371 observed, 509.18 expected, observed/expected ratio (o/e) 0.73, 90% interval 0.67 to 0.79. Synonymous variants: 174 observed, 182.6 expected, observed/expected ratio (o/e) 0.95, 90% interval 0.84 to 1.08.
Homologues: Orthologues: macaque FAXC (100% identical), dog FAXC (99% identical), rat Faxc (99% identical), mouse Faxc (99% identical), rabbit FAXC (98% identical), guinea pig FAXC (98% identical), chimpanzee FAXC (87% identical), tropical clawed frog faxc (83% identical), zebrafish faxcb (67% identical), zebrafish faxca (66% identical), Drosophila melanogaster fax (24% identical), Caenorhabditis elegans faxc-2 (21% identical), and 10 more. Paralogues in human: MTX1 (20% identical), MTX3 (15% identical), MTX2 (15% identical).
Diseases named in the same sentence as FAXC in open-access papers:
FAXC is named in the same sentence as 3 diseases in open-access papers, as found by Europe PMC text mining. Sharing a sentence is not in itself a finding about the gene and the disease. The quoted sentences say what the papers report.
developmental delay (2 papers, 2023 to 2025). "One report describes patients with developmental delay due to a 6q16.1 deletion that included the FAXC gene." (PMID 37627305, 2023).
cholangiocarcinoma (1 paper, 2025). A carcinoma that arises from the intrahepatic biliary tree (intrahepatic cholangiocarcinoma) or from the junction, or adjacent to the junction, of the right and left hepatic ducts (hilar cholangiocarcinoma). "Next, failed axon connection homolog (FAXC), a homolog of Fax in Drosophila, enhanced Anxa2 phosphorylation at mitochondria, which was essential for cholangiocarcinoma (CCA) development." (PMID 39912333, 2025).
FAXC also shares sentences with these, for which no sentence is quoted: deafness (1 paper).